STMN2 (stathmin 2)
Description:
Regulator of microtubule stability. When phosphorylated by MAPK8, stabilizes microtubules and consequently controls neurite length in cortical neurons. In the developing brain, negatively regulates the rate of exit from multipolar stage and retards radial migration from the ventricular zone (By similarity).
Synonyms: SCG10; SCGN10
Tractability: Antibody: UniProt places it where antibodies can reach, with high confidence. PROTAC: UniProt records ubiquitination sites on it; ubiquitination databases record sites on it; its protein half-life has been measured.
Gene: Protein-coding gene on chromosome 8 (79,611,117 to 79,666,159, forward strand). Ensembl gene ENSG00000104435.
Subcellular location: Cytoplasm; Cytoplasm, perinuclear region; Cell projection, growth cone; Membrane; Cell projection, axon; Golgi apparatus; Endosome; Cell projection, lamellipodium
Subcellular location (Human Protein Atlas): Vesicles; Endoplasmic reticulum
Pathways (Reactome):
Signal Transduction: RND1 GTPase cycle
Gene Ontology:
Molecular function: calcium-dependent protein binding; protein binding; tubulin binding
Biological process: cellular response to nerve growth factor stimulus; negative regulation of microtubule depolymerization; negative regulation of microtubule polymerization; negative regulation of neuron projection development; positive regulation of microtubule depolymerization; positive regulation of neuron projection development; microtubule depolymerization; neuron projection development; regulation of microtubule polymerization or depolymerization
Cellular component: cytoplasm; growth cone; lamellipodium; neuron projection; neuronal cell body; perinuclear region of cytoplasm; cytosol; axon; endosome; Golgi apparatus; membrane
Genetic constraint (gnomAD): Loss-of-function variants: 2 observed, 25.14 expected, observed/expected ratio (o/e) 0.0795, 90% interval 0.032 to 0.25. The upper end of that interval is the gene's LOEUF score, 0.25, which puts it in group 1 of 6, group 1 being the genes least tolerant of losing a copy. Missense variants: 114 observed, 223.87 expected, observed/expected ratio (o/e) 0.51, 90% interval 0.44 to 0.6. Synonymous variants: 83 observed, 81.96 expected, observed/expected ratio (o/e) 1.01, 90% interval 0.85 to 1.22.
Homologues: Orthologues: chimpanzee STMN2 (100% identical), dog STMN2 (100% identical), macaque STMN2 (100% identical), mouse Stmn2 (100% identical), rat Stmn2 (97% identical), pig STMN2 (94% identical), rabbit STMN2 (92% identical), tropical clawed frog stmn2 (87% identical), zebrafish stmn2a (76% identical), zebrafish stmn2b (74% identical), Drosophila melanogaster stai (41% identical). Paralogues in human: STMN3 (74% identical), STMN4 (65% identical), STMN1 (58% identical), STMND1 (25% identical).
Diseases named in the same sentence as STMN2 in open-access papers:
STMN2 is named in the same sentence as 63 diseases in open-access papers, as found by Europe PMC text mining. Sharing a sentence is not in itself a finding about the gene and the disease. The quoted sentences say what the papers report.
amyotrophic lateral sclerosis (11 papers, 2021 to 2025). Amyotrophic lateral sclerosis (ALS) is a neurodegenerative disease characterized by progressive muscular paralysis reflecting degeneration of motor neurons in the primary motor cortex, corticospinal tracts, brainstem and spinal cord. "STMN2 is involved in maintaining axonal integrity and loss of STMN2 is associated with amyotrophic lateral sclerosis and various neuropathies." (PMID 40349611, 2025). "In addition, STMN2 loss has been shown to drive axon degeneration, motor neuropathy, and neuromuscular junction denervation and has been implicated in amyotrophic lateral sclerosis pathogenesis." (PMID 38198538, 2024). "A deficiency in STMN2 causes amyotrophic lateral sclerosis (ALS)." (PMID 38132138, 2023). "TDP-43 nuclear depletion in amyotrophic lateral sclerosis (ALS) causes de-repression of cryptic exons (CEs) in multiple transcripts, including UNC13A and STMN2, disrupting synaptic transmission and neurite outgrowth." (PMID 41394711, 2025). "Stathmin-2 (Stmn2) is an axon maintenance factor that is depleted in amyotrophic lateral sclerosis, and replenishment of Stmn2 can restore neurite outgrowth in diseased neurons." (PMID 37236359, 2023). "Genome-wide association studies (GWASs) and the role of the SARM1-negative regulator Stathmin-2 (SCG10) in amyotrophic lateral sclerosis (ALS) also implicate programmed axon degeneration in human disease." (PMID 34910914, 2021). "Notably, proteins significantly decreased under high CE burden included canonical STMN2, ELAVL3, and KALRN, as well as kinesin proteins that are genetically associated with amyotrophic lateral sclerosis." (PMID 40501554, 2025).
proteinopathies (7 papers, 2021 to 2025). "STMN2 encodes an axonal protein that has been extensively studied in the field of TDP-43 proteinopathies, while ARHGAP32, despite being identified in several studies, had not been highlighted for its relevance to the cryptic exon in this gene." (PMID 40478310, 2025). "As expected, we detected a cryptic splicing site in STMN2, a well-established neuronal gene whose mis-splicing occurs in TDP-43-associated proteinopathies." (PMID 41292965, 2025). "Collectively, these studies indicate that a reduction in STMN2 is a critical biomarker for TDP-43 proteinopathy." (PMID 38600555, 2024). "Despite the gap from bench to bedside, STMN2 is a potential therapeutic target for TDP-43 proteinopathy." (PMID 38600555, 2024). "In this context, NPTX2 may represent an important therapeutic target for TDP-43 proteinopathies, along with STMN2 and UNC13A." (PMID 38355792, 2024). "We recently demonstrated the ability of steric binding ASOs to prevent mis-splicing and restore stathmin-2 protein level in TDP-43 deficient neurons and mouse brain, providing support for restoration of STMN2 as a potential therapeutic approach in TDP-43 proteinopathies." (PMID 38175301, 2024). "Previous studies have indicated that ALS-associated TDP-43 mutations or TDP-43 proteinopathy associated with non-familial ALS cause mis-splicing of STMN2 gene transcripts, splicing in a cryptic exon that results in greatly diminished steady-state levels of stathmin-2 mRNA and protein." (PMID 34660586, 2021). "Hence, restoration of stathmin-2, including with ASOs that sterically block the abnormal splicing, emerges as an attractive therapeutic strategy in TDP-43 proteinopathies." (PMID 38175301, 2024).
Alzheimer disease (6 papers, 2023 to 2025). A progressive, neurodegenerative disease characterized by loss of function and death of nerve cells in several areas of the brain leading to loss of cognitive function such as memory and language. "Notably, STMN2 has previously been implicated in neuronal growth regulation and Alzheimer’s disease pathogenesis." (PMID 41188235, 2025). "Collectively these results demonstrate that mis-processing of STMN2 and UNC13A RNAs is a pathological hallmark of TDP-43-associated Alzheimer’s disease, with amygdala and entorhinal cortex being the most affected areas." (PMID 38175301, 2024). "Consistently, STMN2 cryptic exon was only rarely detected in frontal cortex (1/19), occipital cortex (1/19) and cerebellum (4/19) in Alzheimer’s disease patients (Sup." (PMID 38175301, 2024). "TDP-43 pathology follows a stereotypic spread as Alzheimer’s disease progress, and we observe that STMN2 and UNC13A are indeed significantly disrupted in temporal cortex of patients with high Braak stages." (PMID 38175301, 2024). "Indeed, STMN2 cryptic exon was detected in the amygdala of 18 out of 21 Alzheimer’s disease patients positive for phosphorylated TDP-43 and was detected at low levels (Cts above 37; Sup." (PMID 38175301, 2024). "Inversely, STMN2 cryptic exon was detected in 2 out of 17 brains without apparent phosphorylated TDP-43 aggregates which is consistent with reports of TDP-43 nuclear loss without cytoplasmic aggregates in a subset of patients with FTD or Alzheimer’s disease." (PMID 38175301, 2024). "In addition, overexpression of STMN2 in the hippocampus of an Alzheimer’s disease mouse model resulted in decreased amyloid β (Aβ) staining and plaque burden, presumably through STMN2-dependent regulation of the intracellular trafficking and processing of amyloid precursor protein (APP)." (PMID 37614226, 2023). "Collectively this analysis establishes, in a large sample population, that STMN2 and UNC13A transcripts are altered in Alzheimer’s disease patients with advanced Braak stages when the burden of TDP-43 pathology is high." (PMID 38175301, 2024). "Stathmin2 (Stmn2) is a key target of TDP-43 regulation and aberrantly spliced Stmn2 mRNA is found in patients with ALS, frontotemporal dementia, and Alzheimer's Disease." (PMID 38562780, 2024). "Collectively, these results open exciting new avenues to use STMN2 and UNC13A as potential therapeutic targets in a broad range of neurodegenerative conditions with TDP-43 proteinopathy including Alzheimer’s disease." (PMID 38175301, 2024). "We demonstrate, for the first time, that accumulation of STMN2 and UNC13A cryptic exons correlates with TDP-43 pathology in Alzheimer’s disease, independently of amyloid-β or tau pathological burden." (PMID 38175301, 2024). "Analysis of the Mayo Clinic dataset showed a significant enrichment of STMN2 cryptic exon in the temporal cortex of Alzheimer’s disease patients compared to controls and a significant decrease in full-length STMN2 only in Alzheimer’s disease patients with TDP-43 pathology compared to controls." (PMID 38175301, 2024). "We also show, that both STMN2 and UNC13A RNAs are mis-spliced in the amygdala and entorhinal cortex of a substantial fraction of patients with Alzheimer’s disease." (PMID 38175301, 2024). "Here, we identify both STMN2 and UNC13A cryptic exons in Alzheimer’s disease patients, that correlate with TDP-43 pathology burden, but not with amyloid-β or tau deposits." (PMID 38175301, 2024). "stathmin 2(STMN2) encodes a protein that regulates neuronal growth; notably, decreased expression of this gene is often correlated with Alzheimer’s disease and Down syndrome." (PMID 40608007, 2025). "In addition, splicing alterations in STMN-2 and UNC13A have recently been found in Alzheimer’s disease patients." (PMID 40950074, 2025).
Alzheimer disease (continued). "Our study extends on those findings by demonstrating that STMN2 and UNC13A disruption from TDP-43 loss-of-function is detected in large RNA-seq datasets and can distinguish between Alzheimer’s disease patients with and without TDP-43 pathology." (PMID 38175301, 2024). "Abnormal STMN2 transcripts were detected in the amygdala of 20 out of 38 patients and in the entorhinal cortex of 13 out of 27 patients with Alzheimer’s disease, and none of the control individuals (Sup." (PMID 38175301, 2024). "Similarly, our analysis of large RNA-seq datasets from post-mortem tissues also unravels the disruption of STMN2 and UNC13A in Alzheimer’s disease patients." (PMID 38175301, 2024). "Our RNA-seq analysis also shows that the STMN2 cryptic exon is enriched in tissues of Alzheimer’s disease; whereas, no significant enrichment of UNC13A cryptic exon was detected." (PMID 38175301, 2024). "Notably, we observed a correlation between the levels of STMN2 and UNC13A cryptic exons detected in the amygdala of Alzheimer’s disease patients (Spearman r = 0.78, p < 0.0001), strengthening the link between detection of cryptic exons and loss of TDP-43 function." (PMID 38175301, 2024). "We analyzed STMN2 and UNC13A transcripts in bulk RNA-seq from post-mortem brain regions of control and Alzheimer’s disease patients from data available through the Mount Sinai/JJ Peters VA Medical Center Brain Bank (MSBB-AD) and an independent dataset generated at Mayo Clinic." (PMID 38175301, 2024). "Finally, our observations were confirmed by RT-PCR showing the amplification of cryptic exons of both STMN2 and UNC13A transcripts in the amygdala of Alzheimer’s disease patients with TDP-43 pathology, but not in the controls or Alzheimer’s disease patients without TDP-43 pathology." (PMID 38175301, 2024).
frontotemporal dementia (6 papers, 2021 to 2025). Frontotemporal dementia (FTD) comprises a group of neurodegenerative disorders, characterized by progressive changes in behavior, executive dysfunction and language impairment, as a result of degeneration of the medial prefrontal and frontoinsular cortices. "The STMN2 cryptic exon has also been reported to be significantly associated with pTDP-43 levels in frontotemporal lobar degeneration (FTLD)." (PMID 40275359, 2025). "Additionally, reduced STMN2 expression has more recently been reported in the brain of patients with Parkinson’s disease, and frontotemporal dementia." (PMID 33841129, 2021). "Reduced expression of TDP-43 has been associated with the utilization of a intronic cryptic polyadenylation site of the stathmin-2 gene in ALS and frontotemporal dementia (FTD)." (PMID 34769301, 2021).
prion disease (5 papers, 2009 to 2014). A transmissible disease that is caused by a protein that is able to induce abnormal folding of normal cellular proteins, leading to characteristic spongiform brain changes, which are associated with neuronal loss without an inflammatory response. "STMN2 was identified as a prion disease susceptibility factor in vCJD, and ZBTB38 and SORCS1 were identified in a meta-analysis of vCJD, sCJD and kuru resistance GWAS data." (PMID 24833721, 2014). "Presence of single nucleotide polymorphisms (SNPs) in the intron of PRNP, retinoic acid receptor-β protein (RARB), and SCG10/stathmin-like 2, a neuronal growth-associated protein (STMN2) increased the risk of prion diseases." (PMID 23372423, 2012). "Specifically, Mead and others found an association with acquired prion diseases, including vCJD (p = 5.6 × 10(-5)), kuru incubation time (p = 0.017), and resistance to kuru (p = 2.5 × 10(-4)), in a region upstream of STMN2 (the gene that encodes SCG10)." (PMID 20350325, 2010). "Our data provides significant further evidence to support a role for the Rarb genetic locus in prion disease and provides some supporting evidence that Stmn2 may also be implicated." (PMID 21151910, 2010). "Similarly, in the HS mice, Stmn2 gave a significant association with prion disease incubation time (P = 0.04)." (PMID 21151910, 2010). "In a cellular model of mouse prion disease, the expression of Stmn2 was profoundly altered by infection with prions." (PMID 19081515, 2009). "We found an association with acquired prion disease, including vCJD (p=5·6×10−5), kuru incubation time (p=0·017), and resistance to kuru (p=2·5×10−4), in a region upstream of STMN2 (the gene that encodes SCG10)." (PMID 19081515, 2009). "Furthermore, expression of Stmn2 was reduced 30-fold post-infection in a mouse cellular model of prion disease." (PMID 19081515, 2009).
hepatoma (4 papers, 2007 to 2020). "And it was reported that STMN2 is a new target of β-catenin/TCF-mediated transcription in hepatoma cell." (PMID 32510146, 2020). "Of these genes, stathmin-like 2 (Stmn2) was demonstrated to be a direct target of β-catenin/TCF-mediated transcription in hepatoma cells." (PMID 17605829, 2007). "STMN2 is a member of the stathmin gene family, and plays an important part in human hepatoma cells." (PMID 32510146, 2020). "Also STMN2 could be a novel target of beta-catenin/TCF-mediated carcinogenesis in hepatoma cells." (PMID 27980454, 2016).
neuroblastoma (4 papers, 2004 to 2025). Neuroblastoma (NB) is the most common solid, extracranial childhood tumor. "Reducing TDP-43 in human stem cell-derived motor neurons and in neuroblastoma cells results in reduced expression of STMN2 and the induction of an aberrant truncated STMN2 transcript." (PMID 40140908, 2025). "Moreover, in neuroblastoma cells, α-tubulin was shown to be concentrated inone pole of the cells resulting in abnormal process formation, with concomitantup-regulation of the MT-destabilizing protein SCG10 (STMN2)." (PMID 27561110, 2016). "In neuroblastoma cells and human pluripotent stem cell-derived motor neurons, siRNA-mediated knockdown of TDP-43 leads to decreased STMN2 expression that is sufficient to impair axon re-growth after axotomy." (PMID 40140908, 2025).
Parkinson disease (4 papers, 2021 to 2024). A progressive degenerative disorder of the central nervous system characterized by loss of dopamine producing neurons in the substantia nigra and the presence of Lewy bodies in the substantia nigra and locus coeruleus. "Reduced Stmn2 expression has been implicated in human TDP-43 pathologies in ALS and AD, as well as in Parkinson’s disease patients and FTLD-tau patients." (PMID 39312574, 2024).
lung adenocarcinoma (3 papers, 2016 to 2024). A carcinoma that arises from the lung and is characterized by the presence of malignant glandular epithelial cells. "STMN2 encodes a stathmin family member of phosphoproteins and is upregulated in squamous cell carcinoma and lung adenocarcinoma." (PMID 38228050, 2023). "We found that RSPO3, ADAMTS8, DMBT1, DOCK8, STMN2, SPINK6 and TUSC3 were the co-genes of HOXA11-AS in lung adenocarcinoma whereas RSPO3, ADAMTS8, DMBT1, DOCK8, STMN2, SPINK6, TUSC3 and C8orf22 were the co-genes of HOXA11-AS in squamous cell carcinoma." (PMID 27980454, 2016). "For the other five genes (STMN2, SPINK6, TUSC3, LOC100128054, and C8orf22), we found that STMN2, TUSC3 and C8orf22 were upregulated in squamous cell carcinoma and that STMN2 and USC3 were upregulated in lung adenocarcinoma." (PMID 27980454, 2016). "Additionally, ADAMTS8, DMBT1 and DOCK8 were down-regulated in adenocarcinoma and STMN2 and TUSC3 were up-regulated in lung adenocarcinoma (all P < 0.01)." (PMID 27980454, 2016).
neuropathies (3 papers, 2021 to 2025). "The microtubule-stabilising protein superior cervical ganglion 10 (SCG10; also known as stathmin-2 [STMN2]) is a short-lived protein that is constantly supplied to the axon by fast axonal transport and is implicated in TDP-43 neuropathies, in particular ALS." (PMID 34659801, 2021).
squamous cell carcinoma (3 papers, 2016 to 2023). A carcinoma arising from squamous epithelial cells. "We found that RSPO3, ADAMTS8, DMBT1 and DOCK8 were all downregulated in squamous cell carcinoma tissues compared to non-cancerous lung tissues, whereas STMN2, TUSC3 and C8orf22 were upregulated in squamous cell carcinoma (all P < 0.001)." (PMID 27980454, 2016).